APOB (apolipoprotein B)
Diseases named in the same sentence as APOB in open-access papers (continued):
Sharing a sentence is not in itself a finding about the gene and the disease.
metabolic disorders (53 papers, 2011 to 2026). "Germline mutations and polymorphisms in APOB are involved in metabolic disorders, resulting in abnormal lipid metabolism, which is involved in the promotion of pancreatic tumorigenesis." (PMID 37628784, 2023). "ApoB EcoRI mutations altered metabolic diseases that responded to dietary changes in our research sample." (PMID 35732646, 2022). "By reducing apolipoprotein B (apoB) production, increasing fatty acid oxidation, and reducing TG content in the liver, IF may help improve lipid profiles and reduce the risk of metabolic diseases." (PMID 38066628, 2023). "In addition, recent genome-wide association studies identified UGT2B17 as an effector gene for circulating levels of total cholesterol, apolipoprotein B, low density lipoprotein-cholesterol and triglycerides as well as associations between androgen levels and metabolic diseases." (PMID 40264209, 2025). "Our results support a model by which ApoE compensates for the loss of ApoB function through transcriptional activation and post-translational modifications and provide new insights into how hepatic lipid content is regulated by ApoE, whose abnormalities are implicated in metabolic diseases." (PMID 40180213, 2025). "WheresWalker works in multiple species, and was applied to identify mutations from a recent forward genetic screen in zebrafish for genes that modulate ApoB-lipoprotein metabolism, a key factor in the progression of metabolic disease." (PMID 40658698, 2025). "Increased Lp-PLA2 was related with metabolic disorder and was affected by ferritin levels, low-density lipoprotein cholesterol and apolipoprotein B, suggesting its participation in lipid peroxidation." (PMID 35694871, 2022). "Several studies have also suggested that an elevated ApoB/ApoA1 ratio is a more powerful predictor than other lipid fractions for metabolic disorders, including T2DM." (PMID 32505210, 2020). "In conclusion, both the protective effects of multiple APOA-I genetic variants and damaging effects of APOB genetic variations impact the biomarkers of OSA patients.Obviously, the different cumulative effects of genes increase the complexity of metabolic disorders in OSA." (PMID 33005209, 2020). "Additionally, the level of apoB may have interindividual variability depending on concomitant metabolic diseases and may decrease due to the intake of lipid-lowering therapy." (PMID 37685967, 2023). "Primary hypercholesterolemia (PH) is a metabolic disorder characterized by elevated plasma levels of cholesterol, in particular, LDL and apolipoprotein B (apoB)." (PMID 33959024, 2021). "Liver dominates the production and secretion of apolipoprotein B (apoB) and evidence shows that liver malfunction induced by hepatitis B virus (HBV) infection could lead to apolipoprotein metabolism disorders." (PMID 22074108, 2011). "In that ApoA1, the largest component of HDL, and ApoB, which reflects the amount of triglyceride-rich LDL, are meaningful factors in relation to metabolism, the levels of these molecules may explain the state of metabolic diseases like MASLD." (PMID 40507912, 2025). "Maternal metabolic disease did not affect expression of lipid transporter proteins, including ApoA1, ApoB and SR-B1, consistent with our earlier report that expression of glucose and fatty acid transporter genes was also unchanged in diabetic pregnancy-derived yolk sacs." (PMID 36936697, 2023).
metabolic disorders (continued). "Therefore, hepatic MDM2 and its ability to suppress ApoB expression are potential pharmacological targets for the treatment of MAFLD, a metabolic disease currently lacking any effective treatment." (PMID 35524581, 2022).
heart disease (39 papers, 2007 to 2025). "BMI being more strongly associated with heart disease in men than women while also being protective for ApoB, a key heart disease risk factor, requires some explanation." (PMID 40498079, 2025). "We confirm the previously reported causal role of ApoB in ischaemic heart disease even after accounting for more detailed lipid species in multivariate analysis." (PMID 40157129, 2025). "It is said that measuring ApoB can provide a more accurate assessment of heart disease risk than measuring LDL cholesterol alone, as one ApoB particle is present in each LDL molecule." (PMID 37763183, 2023). "The exposure of 57 workers to As showed that there is an increased level of the lipoprotein (a) (LP(a)), a ratio of apolipoprotein-B (Apo-B)/apolipoprotein-A1 (Apo-A1) and Apo-B level and a decreased level of Apo-A1, indicative of high-risk of heart diseases." (PMID 36080424, 2022). "Genetic evidence suggests that both these types of apoB-carrying lipoproteins are causally related to ischaemic heart disease." (PMID 27892411, 2016). "While elevated levels of apoB and reduced levels of apoA1 are associated with increased cardiac disease, serum levels of apoB100 associated VLDL are regulated in turn by Acat2 which stimulates cholesteryl ester secretion into apoB-containing lipoproteins." (PMID 18959802, 2008). "MVMR supported a causal role of ApoB in ischaemic heart disease after accounting for lipid species." (PMID 40157129, 2025). "The ASPirin in Reducing Events in the Elderly trial also demonstrated that PCSK9 pR434W is a member of lipid-lowering PCSK9 and APOB genetic variants that are carried by healthy older individuals (aged ≥ 70 years) and contribute to coronary-heart-disease-free survival." (PMID 36142332, 2022). "Moreover, since vitellogenin-like molecules, such as ApoB, are implicated in heart disease and other aspects of lipid metabolism, the C. elegans larval germ line may provide in roads to the identification of additional associated moieties and receptors." (PMID 39829881, 2025). "In addition, functional mutations in ApoB may explain how polar bears are able to cope with life-long elevated LDL levels that are associated with high risk of heart disease in humans." (PMID 25949827, 2015). "Apolipoprotein B to A1 ratios are strong predictors of heart disease." (PMID 39075463, 2024). "For example, a wide range of potential heart disease risk markers are now considered to be more important than LDL-C, such as inflammation, LDL particle size, Apolipoprotein B and LDL particle number, Lipoprotein(a), lipoprotein ratios and the ratio between triglycerides and HDL." (PMID 34200448, 2021). "It is said that measuring ApoB can provide a more accurate assessment of heart disease risks than measuring LDL cholesterol alone, as one ApoB particle is present in each LDL molecule." (PMID 37763183, 2023).
infection (37 papers, 2010 to 2025). The state of being infected such as from the introduction of a foreign agent such as serum, vaccine, antigenic substance or organism. "In mice, several variants in the Apobec3 gene (apolipoprotein B mRNA-editing complex; A3) confer resistance to infection caused by the MMTV(RIII) strain." (PMID 35336966, 2022). "Importantly, loss of either Nox2 or apoB in the form of LDL is sufficient to promote agrI-mediated invasive infection beyond epithelial and mucosal barriers." (PMID 23459693, 2013). "The sequestration of AIP by apolipoprotein B (which is present in blood that extravasates to site of acute infection) represents a primary host innate immune mechanism to downregulate agr operon expression at the transcriptional level to limit invasive infections caused by S. aureus." (PMID 24164684, 2013). "Three of these experimental models (ST cells, piglet jejunums and 2D organoids) were shown to overexpress apolipoprotein B mRNA editing catalytic polypeptide-like 1 (APOBEC1) during infection." (PMID 41272765, 2025). "The dance between LPS and the lipoprotein subclasses is very complex since, although LPS displays greater affinity for HDL, it can be transferred from HDL (ApoAI) to LDL (ApoB) in response to an acute-phase response to infection." (PMID 38295984, 2024). "Our results show that apolipoprotein B-100 (ApoB-100) and apolipoprotein A-II (ApoA-II) levels were negatively and significantly correlated with the infection intensity." (PMID 36088326, 2022). "Hepatitis C virus (HCV) infection induces the degradation and decreases the secretion of apolipoprotein B (ApoB)." (PMID 34492079, 2021). "Although HCV infection induced oxidative stress in Huh-7 cells, the mRNA level of ApoB was slightly increased at 4 days after infection." (PMID 34492079, 2021). "We analyzed the protein level of ApoB in Huh-7 cells infected with HCV at different multiplicities of infection (MOIs) and found by western blot analysis that the ApoB level decreased in a dose-dependent manner." (PMID 34492079, 2021). "Hepatitis C virus (HCV) infection induces the degradation of apolipoprotein B (ApoB), which is the primary apolipoprotein in low-density lipoprotein (LDL) and very low-density lipoprotein (VLDL)." (PMID 34492079, 2021). "Next, we investigated if the reduced resistance in C57BL/6 mice after attenuation of ApoB secretion impacted the transcriptional response of S. aureus during infection." (PMID 28155859, 2017). "This current work demonstrates that the roles of apoB and Nox2 in defense against agrIII-mediated infections are interdependent." (PMID 23459693, 2013). "We hypothesized that Nox2 and apoB within the context of its serum lipoproteins would differ in the molecular mechanism by which they antagonize agrIII signaling and that this difference would impact the susceptibility to invasive infection in mouse models that lack these innate barriers." (PMID 23459693, 2013). "We used the drug 4APP, which significantly reduces serum apoB levels by inhibition of lipoprotein secretion from the liver, to reduce apoB in wild-type and Nox2−/− mice prior to infection with the agrIII strain MW2." (PMID 23459693, 2013). "Moreover, we found that knockdown of ApoB before infection increased the cellular lipid content and enhanced HCV assembly." (PMID 34492079, 2021). "Not only intracellular but also extracellular infection titers were impaired in BE-KO1 cells compared with those in parental and ApoE-res cells, suggesting that intracellular particle formation is impaired by deficiencies in the expression of ApoB and ApoE." (PMID 25502789, 2014). "Whereas reduction of apoB in the context of LDL is not sufficient to increase susceptibility to agrIII-mediated invasive infection, reduction of apoB in the form of oxLDL is sufficient." (PMID 23459693, 2013).
infection (continued). "If this were the primary function of apoB and oxLDL in our current work we would have expected to see a significant role for reduced serum apoB in susceptibility to an agr negative infection in which LTA would be equivalent and we did not." (PMID 23459693, 2013). "In addition, SARS-CoV-2pp infection decreased the secretion of apoB and apoA1 in transduced cells." (PMID 38727305, 2024). "On the other hand, five genes were down-regulated, that are involved in lipid transport and metabolism (ApoA1, ApoB), apoptosis (Birc3), and blood clotting (coagulation) (Fga, Fgb), potentially indicating an attempt to control lipid accumulation and plaque growth induced by infection." (PMID 26619277, 2015). "Therefore, apoB plays a unique role in inhibition of agr signaling upon initiation of infection." (PMID 23459693, 2013). "We previously reported that both apolipoprotein B, the structural protein of VLDL and LDL, and ROS generated by the phagocyte NADPH oxidase (Nox2), provide unique barriers against S. aureus agrI-mediated virulence and the loss of either significantly increases susceptibility to invasive infection." (PMID 23459693, 2013). "Specifically, the addition of FUC caused a further reduction in mRNA expression levels of NHE2, TRPV6, APOA1, APOA4, APOB, APOC3, and ASS1 compared to PEDV infection alone, while FUC supplementation counteracts PEDV-induced ARG1 upregulation." (PMID 40218394, 2025). "In vitro, infection of Vero-E6 cells with SARS-CoV-2 induced senescence (SenTraGor), DNA damage (γ-H2AX) and increased cytokine (IL-1β, IL-6, CXCL8) and apolipoprotein B mRNA-editing (APOBEC) enzyme expression." (PMID 35086840, 2022). "This was confirmed at the protein level, as infection decreased the amount of secreted AHSG and apolipoproteins APOA1, APOE and APOH, in both HepG2 and Huh7 conditioned media, as well as of APOB, APOC3 and SERPINF2 in Huh7." (PMID 34858876, 2021). "During an acute infection innate response cytokines including type 1 IFNs, tumor necrosis factor (TNF)-α and the apolipoprotein B mRNA editing catalytic polypeptide-like (APOBEC) pathway can suppress virus replication." (PMID 34876153, 2021). "We measured the mRNA levels of apolipoproteins such as ApoA, ApoB and ApoE in the heart and WATs of mice fed a HFD and RD during infection." (PMID 25275627, 2014). "The apolipoprotein B (apo B) messenger RNA (mRNA)-editing, catalytic polypeptide-like 3 (APOBEC3) family of proteins are known to be potent restriction factors and to counteract infection by HIV-1." (PMID 23724012, 2013). "Moreover, Nox2−/− mice treated with 4APP were not more susceptible to infection with an isogenic agr deletion mutant of MW2 (Δagr) compared to controls, confirming that the contribution of Nox2 to apoB-mediated host defense is specific to control of agr-mediated pathogenesis." (PMID 23459693, 2013). "ApoB in the context of oxLDL, and not LDL, provides optimal host defense against S. aureus agrIII infection by binding the secreted signaling peptide, AIP3, and preventing expression of the agr-driven virulence factors which mediate invasive infection." (PMID 23459693, 2013).
genetic disorder (23 papers, 2006 to 2025).
kidney disease (15 papers, 2017 to 2025). "Among polymorphisms in PKCS9 and Apolipoprotein B-100 (ApoB), mutations in ApoB were identified as being associated with greater risk of developing kidney disease among diabetic patients." (PMID 38247511, 2024). "The mediation analysis was performed testing several variables known to be linked to kidney disease, including C-reactive protein, IL-6, uric acid, azotemia, triglycerides, ApoA1, ApoB, and HbA1c, and that resulted associated with mitokines, (data not shown)." (PMID 33131010, 2021). "It has been established that albuminuria is not only an early marker of renal disease, but it also is considered a marker of generalized endothelial damage caused partly by retention of apolipoprotein B-enriched lipoproteins in the arterial wall." (PMID 32752179, 2020). "Immunohistological analyses of apoB/apoE amount in the glomeruli in renal disease found its association with accelerated progression of the renal disease itself." (PMID 31752189, 2019). "ApoB/ApoA-Ι was found to be correlated with the onset of kidney disease." (PMID 34627286, 2021).
autosomal dominant disease (9 papers, 2014 to 2023). Autosomal dominant form of disease. "FHBL is an autosomal dominant disease characterized by low LDL‐C and ApoB levels, which may be due to the mutation of ApoB." (PMID 35712827, 2022). "A mutation in the APOB gene causes familial defective apolipoprotein B-100 (FDB), an autosomal dominant disease of lipid metabolism similar to LDL receptor-mediated FH (non-FDB) characterised by elevated plasma LDL-C levels." (PMID 35295947, 2022).
bacterial infection (5 papers, 2020 to 2022). "For this reason, mice deficient in ApoB are more susceptible to invasive bacterial infection." (PMID 32993120, 2020).
neurodegenerative disease (5 papers, 2011 to 2025). A disorder of the central nervous system characterized by gradual and progressive loss of neural tissue and neurologic function. "Future research focused on regulating APOB may offer promising therapeutic strategies to mitigate the risks associated with both cardiovascular and neurodegenerative diseases." (PMID 40332115, 2025). "We had previously shown that we could deliver a recombinant protein across the CNS through the use of the LDL-R binding domain of ApoB, however, this is the first report showing that this approach can be used in a therapeutic manner to treat a neurodegenerative disease." (PMID 21304989, 2011). "Using the LDL-receptor binding domain of apoB could be an effective way to deliver recombinant proteins across the BBB, and such an approach can be used to treat a neurodegenerative disease." (PMID 27887584, 2016).
neurologic disorders (5 papers, 2020 to 2023). "Apolipoprotein B (ApoB) is believed to be atherogenic and has been associated with neurological diseases, such as the future risk of Parkinson's disease (PD)." (PMID 37122291, 2023). "Similarly, ApoB, ApoA-I, and ApoB/ApoA-I ratios are also associated with many neurological diseases and immune-inflammatory diseases." (PMID 36119695, 2022).
retinopathy (5 papers, 2013 to 2025). "In male subjects only, retinopathy was positively associated with small LDL, LDL particle concentration, apoB concentration, and small HDL, and negatively associated with large LDL, LDL size, large HDL, and HDL size." (PMID 25068073, 2013).
hematologic malignancies (2 papers, 2023 to 2025). "Our finding of a null association between ApoB and risk of hematological malignancy awaits to be validated in future studies, therefore." (PMID 40038140, 2025). "In hematologic malignancies, a deregulation and constitutive expression or activation of proteins of the apolipoprotein B mRNA-editing enzyme catalytic polypeptide (APOBEC) family of deaminases, which are involved in oncogenesis, has been reported." (PMID 36543907, 2023).